SIRPA (signal regulatory protein alpha)
Diseases named in the same sentence as SIRPA in open-access papers (continued):
Sharing a sentence is not in itself a finding about the gene and the disease.
tumor (continued). "Blocking the interaction of CD47 with SIRPα is able to activate phagocytic cells, including M1-like TAMs and dendritic cells (DCs), and increase tumor cells phagocytosis." (PMID 34138357, 2021). "By contrast, high SIRPA expressed in the TAIs in the tumor microenvironment was identified as a potential independent favorable factor (HR = 0.55, p = 0.027)." (PMID 33799989, 2021). "The CD47 overexpressed on the surface of tumor cells can limit the ability of macrophages to engulf tumor cells by interacting with signal regulatory protein α (SIRPα) on macrophages; SIRPα acts as a “don’t eat me” signal." (PMID 34852849, 2021). "The expression level of SIRPα on the intratumoral M-MDSCs of tumor-bearing mice received local IR also significantly increased." (PMID 34068552, 2021). "CD47-induced SIRPα signaling in macrophages and dendritic cells indirectly enhances anti-tumor adaptive T cell immune responses." (PMID 33925464, 2021). "Collectively, these results confirmed that Sirpα−/− macrophages alone are sufficient to induce tumor-specific Tc expansion in situ in irradiated tumors." (PMID 34050181, 2021). "In a mouse model of lymphoma, the bispecific anti-CD47/SIRPα antibody inhibited tumor growth and spread by targeting the multiple myeloid cell types in the tumor." (PMID 34683963, 2021). "CD47 is expressed on tumor cell surface, on a bimodal way (either on 0% or >90% of tumor cells), protecting them from phagocytosis by an interaction with SIRPα on macrophage/dendritic cell surface." (PMID 34925348, 2021). "Intratumoral infusion of Sirpα−/− BMDMs dose-dependently reversed tumor resistance to RT in WT recipient mice." (PMID 34050181, 2021). "Supporting this, irradiated MC38 tumors in Sirpα−/− mice also exhibited an increased frequency of Tc that recognize the MC38-specific tumor neo-antigen ADPGK37." (PMID 34050181, 2021). "Free heme as well as RRx-001 mediated downregulation of CD47 expression on tumor cells and SIRPα expression on macrophages induces a shift from the low phagocytic M1 phenotype to the high phagocytic M2 phenotype in tumor cells." (PMID 33946824, 2021). "SIRPα expression was limited to tumor oligodendrocytes and myeloid cells, while its ligand, CD47, was ubiquitously expressed within the tumor microenvironment." (PMID 34917090, 2021). "In most cases, cessation of tumor growth in Sirpα−/− mice occurred immediately after IR, followed by durable regression and complete clearance of tumors in 4–12 days." (PMID 34050181, 2021). "An anti-human SIRPα mAb was shown to be inert as single agent but in combination with tumor-opsonizing Ab, augmented neutrophil and macrophage antitumor activities in vitro and in vivo." (PMID 34572013, 2021). "CITE-Seq revealed that both SIRPα RNA and protein are prominently expressed on various populations of myeloid cells in GBM tumors, including both microglia- and monocyte-derived tumor-associated macrophages (TAMs)." (PMID 34917090, 2021). "Given that Sirpα−/− macrophages were able to phagocytize cancer cells in vitro after activation by irradiated tumor-produced DAMPs, we next explored the role of Sirpα−/− macrophages combined with IR in mouse tumor clearance." (PMID 34050181, 2021). "Anti-SIRPα mAb alone was ineffective in inhibiting tumor growth in a human SIRPA knock-in mouse (SRG) model." (PMID 33391547, 2021). "When inoculated with a lower number of MC38 cells (5 × 103 cells/mouse), Sirpα−/− mice exhibited significantly slower MC38 tumor growth compared to WT mice, suggesting that Sirpα−/− mice have inherently greater immune control against syngeneic MC38 in vivo." (PMID 34050181, 2021). "In these experiments, Sirpα−/− BMDM-expanded Tc specific for MC38 or KPC (termed Tc-MC38 or Tc-KPC) were i.v. administered to WT mice bearing the same tumor, respectively." (PMID 34050181, 2021).
tumor (continued). "At the same time, several reports pointed out a putative overestimation of the CD47:SIRPα interaction in the interpretation of CD47-mediated modulation of anti-tumor immune response." (PMID 34638503, 2021). "As shown, a dose-escalating amount of MC38 or Pan02 cells was re-engrafted into MC38 or Pan02 tumor-eradicated Sirpα−/− mice." (PMID 34050181, 2021). "SIRPα expression is not only limited to tumor cells but also expressed on tumor infiltrating immune cells." (PMID 34276685, 2021). "Recent studies have emphasized the role of the inhibitory receptor SIRPα in regulating macrophage phagocytosis of tumor cells that highly express CD47." (PMID 33925464, 2021). "CD47 is often overexpressed on tumor cells and interacts with SIRPα on myeloid cells to trigger a ‘don’t eat me’ signal." (PMID 33936033, 2021). "Second, an in vitro coculture system of Sirpα−/− macrophages with tumor-infiltrating lymphocytes (TILs) was established." (PMID 34050181, 2021). "Radioactivity measurements of brain, tumor and peripheral tissues, showed that tissue targeting of the bivalent construct was higher as compared to the monovalent construct in SIRPα+ peripheral organs such as the liver and spleen." (PMID 34917090, 2021). "For example, the pH-responsive exosome nano-bioconjugates composed of M1 macrophages-derived exosomes with antibodies of anti-CD47 and anti-SIRPα through acid-cleavable benzoic-imine bonds has been developed to target the tumor cells." (PMID 34852849, 2021). "All tumor-irradiated Sirpα−/− mice developed inflammatory responses with an elevated serum level of cytokines TNFα, IL-1β, IL-12, and IFNγ, whereas WT mice treated with the same RT regimen did not exhibit similar increases in cytokines." (PMID 34050181, 2021). "In our immunohistochemical studies, it was suggested that SIRPα enabled tumor cells to evade phagocytosis, leading to promoted tumor growth and progression, similar to PD-L1 expression in GCTB patients." (PMID 34285260, 2021). "Several methods have been applied to target TAMs or ATMs to prevent tumor growth or inflammation, such as macrophage depletion, blockade of anti-phagocytic signaling (e.g., Siglec-10 or SIRPα)." (PMID 33763066, 2021). "Blocking CD47 and SIRPα have since become promising avenues to induce killing of tumor cells, with several modalities now being trialed in patients." (PMID 34197341, 2021). "In our recently documented efforts to unravel the GBM immune landscape, multiplex immunohistochemistry revealed that (SIRPα expressing) TAMs are found throughout human GBM tumor tissue." (PMID 34917090, 2021). "To the best of our knowledge, this study is the first one of its kind in that we have specifically investigated the role of the CD47/SIRPα axis in the VES-induced anti-tumour effect." (PMID 34093795, 2021). "CD47 demonstrates its functions via SIRPα to inhibit macrophage phagocytosis, help tumor cells escape immune surveillance, and inhibit the elicitation of both the innate and adaptive immune responses." (PMID 34367975, 2021). "The tumor-specific (p15E-reactive) Tc and TEM persisted in irradiated Sirpα−/− mice and were readily detectable in mouse peripheral blood and the spleen two weeks after tumor eradication." (PMID 34050181, 2021). "Immunotherapies blocking the CD47-SIRPα pathway can be achieved with antagonist molecules binding to SIRPα on macrophages or to CD47 on tumor cells." (PMID 34572013, 2021). "These exosome nano-bioconjugates can release the antibodies after the selective cleavage in the acid tumor microenvironment that block the interaction between SIRPα and CD47, and thereby improve phagocytosis of macrophages." (PMID 34852849, 2021). "We show that the presence of activated Sirpα−/− macrophages in tumors alone shifts the post-radiation response of TME from pro-tumor wound-healing to tumor elimination." (PMID 34050181, 2021).
tumor (continued). "Sirpα−/− BMDMs were first incubated with irradiated MC38 or PDA tumor dissociates for activation and phagocytosis of tumor antigens." (PMID 34050181, 2021). "The physiopathological mechanism of this association appears intuitive, since higher levels of CD47 will more efficiently inhibit SIRPα on macrophages and therefore the tumor will evade innate immune response." (PMID 34195295, 2021). "Monoclonal antibodies blocking the interaction between CD47 on tumor cells and SIRPα on innate immune cells is another interesting direction for future research." (PMID 34094963, 2021). "CD47 and SIRPα expression depend on the tumor histotype with a high frequency of expression in DDLPS and chordoma, as assessed by immunohistochemistry." (PMID 34925348, 2021). "Signal regulatory protein α (SIRPα) on macrophages serves as a receptor of CD47 to transduce CD47/SIRPα axis mediated inhibitory function of macrophage phagocytosis of tumor cells." (PMID 33763066, 2021). "This suggests that NTP treatment of the tumor can reduce the ability of CD47 to bind to SIRPα on innate immune cells." (PMID 33540720, 2021). "Its interaction with SIRPa, a molecule expressed on macrophages, sends a “don’t eat me” signal that allows tumor cells to escape phagocytosis." (PMID 34768921, 2021). "Next, we generated SIRPα-specific nanobodies that bind the SIRPα+ tumor myeloid populations and revealed that the monovalent nanobody format can efficiently target mouse GBM tumors in vivo." (PMID 34917090, 2021). "SIRPα on the exosome surface enhanced the phagocytic ability of bone-marrow-derived macrophages and effectively inhibited cancer growth in a tumor xenograft model." (PMID 34503245, 2021). "Uptake values of 99mTc-labeled control Nb R3B23 or anti-SIRPα nanobodies in GL261 tumor-bearing mice based on dissection at 1 h 45 min post injection." (PMID 34917090, 2021). "Both Cl2MDA-liposomes and αCSF1R antibodies abrogated the efficacy of RT with respect to suppressing tumor growth in and enhancing the survival rate of Sirpα−/− mice, suggesting a key role for intratumoral Sirpα−/− macrophages in responding to RT." (PMID 34050181, 2021). "We also found that extensive PMN infiltration in irradiated tumors in Sirpα−/− mice was positively correlated with rapid tumor elimination, supporting the tumoricidal role of these proinflammatory PMNs." (PMID 34050181, 2021). "CD47 can trigger evasion of tumor cells from macrophage recognition by interacting with signal regulatory protein alpha (SIRPα), has been another hot target for tumor immunotherapy." (PMID 34288805, 2021). "Attractive targets for gene editing include regulatory proteins that block anti-tumor functions, such as signal regulatory protein-α (SIRPα)." (PMID 34899748, 2021). "CD47 on the tumor cell surface binds to SIRPα on the surface of macrophages, which activates the Src homology region 2 (SH2) domain phosphatases SHP1 and SHP2 and thereby transmits a “don’t eat me” signal to macrophages." (PMID 35070992, 2021). "CD47/Signal regulatory protein α (SIRPα) is a crucial immune checkpoint pathway that is crucial for maintaining self-stability and eliminating tumor cells." (PMID 34943817, 2021). "Injection of the sera from tumor-eradicated Sirpα−/− mice successfully prevented nascent tumor formation in WT recipient mice." (PMID 34050181, 2021). "It is well recognized that the innate immune regulator CD47 and the adaptive immune checkpoint PD-L1 regulate tumor immune responses through the SIRPα/CD47 and PD-1/PD-L1 pathways, respectively." (PMID 33731702, 2021). "SIRPα is a regulatory membrane glycoprotein expressed on the macrophage membrane that accumulates at a phagocytic synapse between macrophages and tumor cells upon CD47 binding." (PMID 34675914, 2021). "Another set of preclinical data show TTI-622, a new human SIRPα linked to human IgG4, induces ADCP in a panel of haematological and solid tumour cells, with a superior affinity for tumour cells than for platelets." (PMID 33430146, 2021).
tumor (continued). "In LPS, the prognostic impact of CD47/SIRPα signaling in patients has not been reported, although many patients have been found to have CD47 expression in tumor cells, as well as infiltrating SIRPα positive macrophages." (PMID 33893830, 2021). "Immunostaining of irradiated tumor tissues from Sirpα−/− mice (3-days post-IR) revealed numerous Tc distributing in the tumor core and throughout the invasive edge." (PMID 34050181, 2021). "Currently, disrupting the CD47/SIRPα interaction has become a new antitumor immunotherapy strategy that induces the phagocytosis and elimination of tumor cells." (PMID 34943817, 2021). "SIRPα inhibits the phagocytic activity of macrophages when interacting with its ligand CD47 which can be expressed on tumor cells." (PMID 34440251, 2021). "CD47 expressed on the tumor cells serves as a ligand for the SIRPα immune inhibitory receptor, which is expressed on macrophages." (PMID 33629544, 2021). "Tight engagements between activated Sirpα−/− BMDMs and tumor-specific Tc were seen within 1 h of co-incubation, in a fashion reminiscent of mature dendritic cells forming antigen-presenting conjugates with T cells." (PMID 34050181, 2021). "Based on this mechanism, exosomes expressing SIRPα on their surface to inhibit CD47 functions of tumor cells were developed." (PMID 34503245, 2021). "A CD47/SIRPα blockade provokes antitumor activity by inducing tumor cell phagocytosis by macrophages and activating the cross-presentation of tumor antigens to CD8+ T cells by DCs." (PMID 35008305, 2021). "In line with its role in inducing rapid tumor regression, high dose rate RT (2 Gy/min, 20 Gy) exaggerated the inflammatory responses in Sirpα−/− mice, which sometimes compromised mouse survival." (PMID 34050181, 2021). "The binding of aberrantly expressed CD47 on tumor cells to signal regulatory protein-alpha (SIRPA) on macrophages allows tumor cells to evade immune destruction." (PMID 33799989, 2021). "The CD47 receptor is highly expressed on tumor cells and provides a “don’t eat me” signal via interacting with the N-terminus of signal regulatory protein alpha (SIRPα) on macrophages and other myeloid cells to block phagocytosis." (PMID 34452008, 2021). "For example, increased expression of CD47 by tumor cells triggers an inhibitory signaling in macrophages through the immune checkpoint SIRPα, that limits macrophage-dependent phagocytosis and lymphocyte chemotaxis." (PMID 34276698, 2021). "The prevailing model proposes that high CD47 expression on tumor cells engages the inhibitory counter-receptor SIRPα on phagocytes to prevent tumor cell killing." (PMID 33925464, 2021). "The large expansion of tumor-specific Tc was critical for durable tumor regression, as depletion of Tc (by αCD8), but not CD4 T helper cells (Th; by αCD4), diminished the efficacy of RT in tumor-bearing Sirpα−/− mice." (PMID 34050181, 2021). "Further, CD47, a cell transmembrane protein expressed in ESCC tumor cells, can inhibit CD8+ T-cell infiltration and anti-tumor immune responses in a DC-dependent manner, by interacting with signal regulatory protein-α (SIRPα), expressed in DCs." (PMID 33995371, 2021). "Most tumors harbor surface CD47 that interacts with signal-regulating protein α (SIRPα) on phagocytes, which reduces the ability of macrophages to phagocytose tumor cells." (PMID 33537081, 2021). "CD47 molecules expressed on tumor cells interact with signal-regulatory protein alpha (SIRPα) on TAMs to prevent phagocytosis, enabling the escape of innate immune surveillance." (PMID 33919979, 2021). "Exosome-signal regulatory protein α (SIRPα) can interact with cluster of differentiation 47 (CD47) exiting in the tumor cells surface, thus restricting macrophages from engulfing tumor cells." (PMID 35047512, 2021).
tumor (continued). "After 18 h, the tumor antigen-loaded Sirpα−/− BMDMs, which by then also exhibited proinflammatory characteristics and increased immunogenic antigen presentation machinery, were cocultured with TILs isolated from the mice bearing the same type of tumor." (PMID 34050181, 2021). "Based on the benefits achieved for the treatment of other malignancies, CD47-targeting antibody and human (or murine) SIRPα-Fc have been used to access the anti-tumor effect of GBM by blocking CD47-SIRPα axis in vitro and in vivo." (PMID 32824974, 2020). "In mouse TAMs, we demonstrated that the binding of the Elk-1 protein and Sirpα DNA increased with tumor progression." (PMID 32296015, 2020). "Antibodies blocking the CD47/SIRPα signal pathway can effectively stimulate macrophage-mediated phagocytosis of tumor cells, which becomes a promising approach for tumor immunotherapy." (PMID 31931812, 2020). "For instance, one recent study showed that the anti-tumor efficiency of CD47/SIRPα blockades can be reinforced upon combination with CTLA-4, PD-L1 or other ICI blockers." (PMID 32824974, 2020). "Potent anti-tumor activities were associated with macrophage-mediated phagocytosis induced by HuNb1-IgG4, which is due to blockade of CD47/SIRPα." (PMID 31931812, 2020). "CD47 has been found expressed on many tumor cells, and it can bind with signal regulatory protein α (SIRPα) on the membrane surface of macrophages, which down-regulates macrophage phagocytosis of tumor cells." (PMID 33251232, 2020). "Therapies that block the interaction of CD47 and SIRPα have been shown to stimulate tumour cell phagocytosis in vitro and induce anti-tumour immune responses in vivo, and CD47 blockade is being tested in clinical trials." (PMID 31205227, 2020). "Namely, stimulation of the CD47/ signal regulatory protein alpha (SIRPα) axis abolishes phagocytosis of malignant cells and macrophage cytotoxicity against tumor cells." (PMID 32610582, 2020). "The induction of antitumor responses depends on SIRPα+CD11c+ DCs, which exhibit rapid expansion following introduction of CD47-deficient tumor cells." (PMID 31996683, 2020). "The T lymphocytes activated by SIRPα-silenced DCs significantly decreased the tumor mass compared with controls in which progressive tumor growth was observed." (PMID 32411788, 2020). "By interacting with CD47, a “don’t eat me” protein, the SIRPα‒CD47 complex blocks the phagocytosis of tumor cells." (PMID 33126572, 2020). "Signal regulatory protein alpha (SIRPα)–CD47 is a classical molecule match to prohibit the phagocytosis of macrophages in tumor immune escape." (PMID 33505964, 2020). "CD47 is highly expressed on multiple tumor cell surface membranes involved in regulating macrophage phagocytosis via binding SIRPα to protect host cells from being eliminated." (PMID 33469516, 2020). "Considering the potential of CD47-SIRPα signaling in regulation of DC function, we analyzed the changes in SIRPα+ DCs following tumor cell vaccination." (PMID 31996683, 2020). "Other bispecific agents (LicMABs) have been produced by the binding domain of SIRPα to a tumor-targeting antibody such as anti-CD33 promoted elimination of AML tumor cells." (PMID 32677994, 2020). "Exosomes with SIRPα expression showed higher tumor growth inhibition compared to the same dose of protein-scaffold-based nanocages, such as ferritin-SIRPα-nanocages." (PMID 32403320, 2020). "Consistent with the expression profile of Sirpα, the mRNA levels of Elk-1 in TAMs increased with tumor progression in MC-38- and CT-26 cell-based subcutaneous tumor models and in spontaneous tumor models." (PMID 32296015, 2020). "CD47 is expressed on tumour cells and binds to SIRPα, expressed on myeloid cells, preventing phagocytosis." (PMID 31996683, 2020). "The production of EV bearing SIRPα molecules has been shown to successfully hamper the tumor “don’t-eat-me” signal in favor to macrophage phagocytosis." (PMID 33117718, 2020).